MTRR (5-methyltetrahydrofolate-homocysteine methyltransferase reductase)
Diseases named in the same sentence as MTRR in open-access papers (continued):
Sharing a sentence is not in itself a finding about the gene and the disease.
Stroke (3 papers, 2011 to 2017). Sudden impairment of blood flow to a part of the brain due to occlusion or rupture of an artery to the brain. "The only previous investigation of MTRR polymorphism frequency in the Turkish population was conducted in children with stroke; however, the frequency of homozygous GG variant (4%) for this enzyme in that study was lower than we observed in ours." (PMID 27094381, 2017).
ventricular septal defect (3 papers, 2013 to 2025). The presence of a defect (opening) in the septum that separates the two ventricles of the heart. "We describe the findings of genotyping the polymorphisms in the MTRR, GATA4, VEGF and ISL1 genes in Pakistani children with isolated ventricular septal defects." (PMID 33757570, 2021).
dementia (2 papers, 2017 to 2022). Loss of intellectual abilities interfering with an individual's social and occupational functions. "It has been shown that mutations in 5-methyltetrahydrofolate-homocysteine methyltransferase reductase (MTRR) gene in humans led to developmental delay, brain atrophy, seizures, hypotonia and dementia." (PMID 28649192, 2017).
Down syndrome (2 papers, 2023 to 2024). "The aim of this study was to investigate the association between the MTHFR rs1801133, MTHFR rs1801131, MTRR rs1801394, DNMT1 rs2228611, DNMT3A rs1550117, DNMT3B rs1569686, and DNMT3B rs2424913 gene polymorphisms and congenital heart defects in Down syndrome (DS) individuals." (PMID 36980848, 2023).
gastric cancer (2 papers, 2014 to 2020). A primary or metastatic malignant neoplasm involving the stomach. "In addition, our study suggested potential OR variations across strata of alcohol consumption, including associations of MTRR rs1801394 with esophageal and stomach cancer, and MTR rs1805087 with liver cancer." (PMID 25337902, 2014). "In addition, we detected potential heterogeneity across alcohol drinking status for ORs relating MTRR rs1801394 to esophageal (posterior homogeneity P = 0.005) and stomach cancer (posterior homogeneity P = 0.004), and ORs relating MTR rs1805087 to liver cancer (posterior homogeneity P = 0.021)." (PMID 25337902, 2014).
leukemia (2 papers, 2017 to 2022). A malignant (clonal) hematologic disorder, involving hematopoietic stem cells and characterized by the presence of primitive or atypical myeloid or lymphoid cells in the bone marrow and the blood. "However, polymorphism in the MTRR gene has been widely investigated for the risk of leukemia." (PMID 36292614, 2022).
male infertility (2 papers, 2015 to 2021). The inability of the male to effect fertilization of an ovum after a specified period of unprotected intercourse. "Furthermore, the MTR A2756G and MTRR A66G mutations were potentially linked with a risk of male infertility." (PMID 26549413, 2015). "We aimed to determine whether 5, 10-methylenetetrahydrofolate reductase (MTHFR) C677Tand methionine synthase reductase (MTRR) A66G genotypes are associated with male infertility in Iranian men andto evaluate its effect on seminal levels of folate and vitamin B12." (PMID 33497043, 2021). "Therefore, it can be speculated that mutations in MTHFR, MTR and MTRR could be possible candidates for male infertility because of the vital functions of folate-related enzymes." (PMID 26549413, 2015). "MTR A2756G and MTRR A66G were potential candidates in the pathogenesis of male infertility, but more case-control studies were required to avoid false-positive outcomes." (PMID 26549413, 2015).
meningioma (2 papers, 2014 to 2017). A generally slow growing tumor attached to the dura mater. "Our results are consistent with a previous meta-analysis showing that MTRR rs1801394 polymorphism may increase the risk of meningioma." (PMID 28915669, 2017). "Therefore, we conducted the present meta-analysis to investigate the association of MTRR rs1801394 polymorphism with meningioma and provide updated information on the association of MTR rs1805087 polymorphism with meningioma." (PMID 24748989, 2014). "Several epidemiological studies suggested that methionine synthase (MTRR) rs1801394 and methionine synthase reductase (MTR) rs1805087 polymorphisms may be involved in the risk of meningioma in adults; however, the results from different case-control studies have been inconsistent." (PMID 24748989, 2014). "Several molecular epidemiological studies have been conducted to investigate the association of MTRR rs1801394 and MTR rs1805087 polymorphisms with meningioma." (PMID 24748989, 2014). "Therefore, we performed the present meta-analysis to investigate the association of the MTRR rs1801394 and MTR rs1805087 polymorphisms with susceptibility to meningioma." (PMID 24748989, 2014).
ovarian carcinoma (2 papers, 2016 to 2024). A malignant neoplasm originating from the surface ovarian epithelium. "In addition, elevated expression of the oncogenic promoter methionine synthase reductase (MTRR) has been found in ovarian cancer, and cisplatin resistance can be inhibited by inhibiting MTRR expression which can reduce autophagy." (PMID 39695078, 2024). "Furthermore, methionine synthase reductase (MTRR), which was a promoter of carcinogenesis, was found to be increased in ovarian carcinoma." (PMID 27825125, 2016).
pancreatic cancer (2 papers, 2016 to 2018). "However, rs162049 in the MTRR gene, which encodes enzymes responsible for DNA methylation, has been shown to be associated with the susceptibility to pancreatic cancer in one previous Japanese case-control study." (PMID 27473058, 2016). "In addition, expression of the YY genotype in the methionine synthase reductase (MTRR) H595Y SNP and the 3Rc/3Rc genotype in thymidylate synthase (TYMS) also increased the risk for development of pancreatic cancer." (PMID 29474406, 2018).
preeclampsia (2 papers, 2022 to 2024). Preeclampsia is a hypertensive disorder of pregnancy that is characterized by new-onset hypertension with proteinuria presenting after 20 weeks of gestation, and depending on mild or severe forms may initially present with severe headache, visual disturbances, and hyperreflexia. "From 3082 patients with preeclampsia tested for MTRR gene mutations, 756 (24.5%) had confirmed MTRR A66G polymorphism." (PMID 39336076, 2024). "This study aimed to evaluate the prevalence of methionine synthase (MTR), methionine synthase reductase (MTRR), and methylenetetrahydrofolate reductase (MTHFR) genes’ polymorphisms among ethnic Kazakh women with preeclampsia." (PMID 39336076, 2024). "In this study, the highest prevalence of MTR A2756G, MTRR A66G, and MTHFR C677T polymorphism were registered among women with preeclampsia in the 30–34 and 35–39 age groups." (PMID 39336076, 2024). "Thus, the study’s aim was to evaluate the prevalence of methionine synthase (MTR), methionine synthase reductase (MTRR), and methylenetetrahydrofolate reductase (MTHFR) genes’ polymorphisms among ethnic Kazakh women with preeclampsia." (PMID 39336076, 2024). "Moreover, multiple studies found that genetic polymorphisms, particularly MTR A2756G, MTRR A66Gm, and MTHFR C677T, are associated with preeclampsia and severe preeclampsia." (PMID 39336076, 2024). "In the context of this genetic study on folate metabolism genes’ polymorphisms (MTR, MTRR, and MTHFR) among ethnic Kazakh women with preeclampsia, an HWE test would evaluate whether the observed genotype frequencies match the expected frequencies based on the genetic principles." (PMID 39336076, 2024). "MTRR A66G and MTR A2756G have been proved to be associated with increased homocysteine levels, and a certain concentration of homocysteine could cause endothelial cell dysfunction and oxidative stress, which is positively related to PTB, LBW, and preeclampsia." (PMID 35631247, 2022). "Significant expressions of MTRR A66G and MTHFR C677T were seen among the study participants and were related to preeclampsia." (PMID 39336076, 2024). "Low levels of folate and high levels of homocysteine are found among women with preeclampsia; thus, this fact proves an essential fore of MTR, MTRR, and MTHFR enzymes in coagulation homeostasis and pregnancy maintenance." (PMID 39336076, 2024).
aneurysm (1 paper, 2021). Bulging or ballooning in an area of an artery secondary to arterial wall weakening. "A previous report indicated that polymorphisms in folate cycle enzymes, MTHFR, MTR, and MTRR, were related to aneurysm severity and dissection potential in MFS patients." (PMID 34769168, 2021).
autism spectrum disorder (1 paper, 2024). A spectrum of developmental disorders that includes autism, and Asperger syndrome. "ASD: Autism Spectrum Disorder; AT: Autoimmune Thyroiditis; MTHFR: Methylenetetrahydrafolatreductase; TCN1: Transcobalamin 1; TCN2: Transcobalamin 2; MTRR: Methionine synthase reductase; PEMT: Phosphoethanolamine N-Methyltransferase." (PMID 38807972, 2024).
benign ovarian tumors (1 paper, 2019). "The expression of FOLR1, DHFR, and MTRR was evaluated in 80 cases of primary OC, 50 cases of benign ovarian tumors, and 30 normal ovarian tissues." (PMID 31049278, 2019).
cervical cancer (1 paper, 2018). A primary or metastatic malignant neoplasm involving the cervix. "The purpose of this study was to illustrate the relationship between methylenetetrahydrofolate reductase (MTHFR) polymorphisms or methionine synthase reductase (MTRR) polymorphisms and cervical cancer." (PMID 29740106, 2018).
cleft lip (1 paper, 2020). Congenital defect in the upper lip where the maxillary prominence fails to merge with the merged medial nasal prominences. "Recently, many efforts have been made to find the genetic variants in folate pathway genes such as MTHFR (methylenetetrahydrofolate reductase), MTRR (Methionine synthase reductase), TCN2 (transcobalamin 2), and BHMT (betaine-homocysteine methyltransferase) and their susceptibility to cleft lip." (PMID 32124929, 2020).
colon cancer (1 paper, 2022). "For the MTRR gene, the relationship between haplotype G-C/G-T, composed of rs1801394 (exon 2) and rs13181011 (intron 3), and the worse survival of colon cancer patients provides good evidence for a harmful effect of the rs1801394 G allele on survival." (PMID 36364857, 2022).
Cri-du-chat syndrome (1 paper, 2022). Monosomy 5p, also known as Cri du chat syndrome, is a rare autosomal deletion syndrome characterized by a mewing cry (cri du chat) in infancy, multiple congenital anomalies, intellectual disability, microcephaly, and facial dysmorphism. "It has been previously suggested that MTRR (in the 15.31 region of 5p), a gene linked to folate and methionine metabolism that contributes to the supply of methyl groups for DNA methylation, may have a role in the pathogenesis of Cri du chat syndrome." (PMID 36242045, 2022).
gestational diabetes (1 paper, 2025). Carbohydrate intolerance first diagnosed during pregnancy. "Moreover, a recent study indicated that personalized folic acid supplementation based on polymorphisms in the MTHFR and MTRR genes could reduce the risk of gestational diabetes." (PMID 41473191, 2025).
hypothyroidism (1 paper, 2025). Abnormally low levels of thyroid hormone. "MTRR A66G and MTR A2756G polymorphisms are associated with hypothyroidism and metabolic comorbidities, both individually and in genotype combinations." (PMID 41150742, 2025). "This study examined associations between hypothyroidism and polymorphisms in MTHFR (C677T–rs1801133, A1298C–rs1801131), MTRR (A66G–rs1801394), and MTR (A2756G–rs1805087) genes." (PMID 41150742, 2025).
keloid (1 paper, 2025). An irregularly shaped, elevated mark on the skin caused by deposits of excessive amounts of collagen during wound healing. "Heat maps showed decreased expression of genes involved in Hcy catabolism, including CBS, MTR, 5-methylenetetrahydrofolate homocysteine methyltransferase reductase (MTRR), methylenetetrahydrofolate reductase (MTHFR), and methionine adenosyltransferase 1a (MAT1A) in keloids." (PMID 39919369, 2025).
lung adenocarcinoma (1 paper, 2026). A carcinoma that arises from the lung and is characterized by the presence of malignant glandular epithelial cells. "We found that the up-regulation of methionine synthase reductase (MTRR) by regulating the phosphorylation of vimentin Ser56 in SCAPEP is a key mechanism driving the aggressiveness of SCAPEP -high lung adenocarcinoma." (PMID 42091858, 2026).
pulmonary fibrosis (1 paper, 2025). Chronic progressive interstitial lung disorder characterized by the replacement of the lung tissue by connective tissue, leading to progressive dyspnea, respiratory failure, or right heart failure. "Through both Hcy supplementation and MTRR knockdown experiments, we demonstrated that HHcy promotes pulmonary fibrosis." (PMID 40990430, 2025). "To evaluate the therapeutic potential of MTRR, we investigated whether its overexpression could prevent pulmonary fibrosis in experimental models." (PMID 40990430, 2025). "Conversely, promoting Hcy catabolism, either through MTRR overexpression or folate administration, reduced STX17 homocysteinylation and ameliorated pulmonary fibrosis." (PMID 40990430, 2025).
sickle cell disease (1 paper, 2022). Sickle cell anemias are chronic hemolytic diseases that may induce three types of acute accidents: severe anemia, severe bacterial infections, and ischemic vasoocclusive accidents (VOA) caused by sickle-shaped red blood cells obstructing small blood vessels and capillaries. "Bantu, Afro-related ethnolinguistic cultural groups, and Latin America have a similar low proportion of pathogenic variants in most of the sickle cell disease-specific genes, except in MY O 7B, CPS1, COL6A3, MTRR, SLC22A5, ABCC1, and RPL3L." (PMID 35812734, 2022).
stomatitis (1 paper, 2016). Inflammation of the oral mucosa due to local or systemic factors. "The best overall GMDR model for stomatitis suggested an interaction between MTRR rs1801394 and MTHFR rs1801133 polymorphisms." (PMID 27452984, 2016).
toxicity (1 paper, 2024). The degree to which an agent can damage an organism. "For the primary outcome, we found that the allele A of MTRR rs1801394 was significantly related to renal toxicity (odds ratio 2.084 (1.001–4.301), p-value 0.047)." (PMID 38678107, 2024).
urethritis (1 paper, 2018). Inflammation of the urethra. "In contrast, one isolate from the U.S. NmNG urethritis clade collected in 2015 (M38896) had a gonococcal-like mtrR sequence (allele type 39) that is also associated with elevated azithromycin MICs of 2 μg/mL." (PMID 29499642, 2018).
cancer (8 papers, 2007 to 2023). A tumor composed of atypical neoplastic, often pleomorphic cells that invade other tissues. "MTHFR, MTR and MTRR genes play key roles in folate metabolism pathway and were most examined in cancer risk and prognosis." (PMID 33033524, 2020).
infection (6 papers, 2015 to 2020). The state of being infected such as from the introduction of a foreign agent such as serum, vaccine, antigenic substance or organism. "Mutations in mtrR and its promoter, which alleviate repression of the MtrCDE multidrug efflux pump, are advantageous for fitness during colonization of a mouse model of infection." (PMID 32438866, 2020). "It has also been proposed that mutant (including frameshifted) mtrR alleles may be advantageous for N. gonorrhoeae during infection." (PMID 27918265, 2016). "In order to test this hypothesis, we ectopically expressed a WT copy of the mtrR gene, which encodes the repressor of the mtrCDE efflux pump operon, in N. gonorrhoeae strain H041, the first reported gonococcal strain to cause a third-generation-cephalosporin-resistant infection." (PMID 31409679, 2019). "Thus, we hypothesized that ectopic expression of mtrR in these strains would decrease levels of MtrCDE and render gonococci more susceptible to antibiotics both under laboratory conditions and during experimental infection." (PMID 31409679, 2019). "We propose that transcriptional control of gonococcal genes through the action of MtrR and GdhR contributes to fitness of N. gonorrhoeae during infection." (PMID 28400529, 2017). "Along with its capacity to control expression of other “off target” genes, the global regulatory action of MtrR likely serves to fine-tune important physiological processes of gonococci during infection." (PMID 26078871, 2015). "These specific responses are likely mediated, in part, by DNA-binding transcription factors, several of which were found to be expressed and regulated during infection, including Fur and MtrR, and an ArsR-like regulator." (PMID 26244506, 2015).
tumor (3 papers, 2014 to 2021). "Quantitative analysis of Western blotting analysis showed that FOLR1 and MTRR have the highest expression in OC tissues, while DHFR has the highest expression in benign tumor tissues." (PMID 31049278, 2019). "The MTRR A66G (rs1801394) polymorphism is a well-recognized locus associated with enzyme function and may affect the interaction of MTRR and MTR, participating in tumor formation." (PMID 24748989, 2014).
benign tumors (1 paper, 2019). "In order to detect the location, FOLR, DHFR, and MTRR expression in clinical samples was assessed by immunohistochemical staining of sections isolated from 10 OC, 10 patients with benign tumors OC, and 10 patients with normal ovaries." (PMID 31049278, 2019).
MTRR also shares sentences with these, for which no sentence is quoted: schizophrenia (4 papers); dyslipidemia (3); fetal growth restriction (3); macrocytic anaemia (3); metabolic disorder (3); cardiovascular disease (2); colorectal cancer (2); developmental delay (2); Methylmalonic aciduria (2); optic disc edema (2); polycystic ovary syndrome (2); acute lymphoblastic leukemia (1); adrenoleukodystrophy (1); alcoholism (1); Alzheimer disease (1); anaemia (1); anencephaly (1); atherosclerosis (1); atrial septal defect (1); Autoimmune Thyroiditis (1); biotinidase deficiency (1); bipolar disorder (1); Brain atrophy (1); Chronic Myeloid Leukemia (1); clear cell renal cell carcinoma (1); cobalamin deficiency (1); colorectal adenoma (1); diabetes (1); endothelial dysfunction (1); epilepsy (1).
A further 21 diseases each share a sentence with MTRR in 1 paper.